RNU6-621P (RNA, U6 small nuclear 621, pseudogene)
Gene: Small nuclear RNA gene on chromosome 3 (197,994,601 to 197,994,709, forward strand). Ensembl gene ENSG00000201622.
Homologues: Orthologues: chimpanzee U6 (99% identical), macaque U6 (93% identical), guinea pig U6 (87% identical), pig U6 (81% identical). Paralogues in human: RNU6-669P (92% identical), RNU6-41P (90% identical), RNU6-166P (89% identical), RNU6-35P (89% identical), RNU6-1060P (88% identical), RNU6-1145P (88% identical), RNU6-1152P (88% identical), RNU6-12P (88% identical), RNU6-1316P (88% identical), RNU6-13P (88% identical), RNU6-15P (88% identical), RNU6-188P (88% identical), and 1286 more.